MRPL20 (mitochondrial ribosomal protein L20)
Synonyms: L20mt; MRP-L20; FLJ10024; bL20m
Tractability: Small molecule: a structure with a bound ligand is known. PROTAC: ubiquitination databases record sites on it; its protein half-life has been measured.
Gene: Protein-coding gene on chromosome 1 (1,401,908 to 1,407,306, reverse strand). Ensembl gene ENSG00000242485.
Subcellular location: Mitochondrion
Subcellular location (Human Protein Atlas): Mitochondria
Pathways (Reactome):
Metabolism of proteins: Mitochondrial ribosome-associated quality control; Mitochondrial translation elongation; Mitochondrial translation initiation; Mitochondrial translation termination
Gene Ontology:
Molecular function: protein binding; RNA binding; structural constituent of ribosome; rRNA binding
Biological process: mitochondrial translation; translation
Cellular component: mitochondrial large ribosomal subunit; mitochondrial ribosome; mitochondrion; large ribosomal subunit; mitochondrial inner membrane; ribosome
Genetic constraint (gnomAD): Loss-of-function variants: 21 observed, 21.44 expected, observed/expected ratio (o/e) 0.98, 90% interval 0.69 to 1.41. The synonymous counts are far from expectation, so gnomAD's model fits this gene poorly and the ratio says little. Missense variants: 252 observed, 192.64 expected, observed/expected ratio (o/e) 1.31, 90% interval 1.18 to 1.45. Synonymous variants: 104 observed, 74.93 expected, observed/expected ratio (o/e) 1.39, 90% interval 1.18 to 1.63.
Homologues: Orthologues: guinea pig MRPL20 (90% identical), mouse Mrpl20 (88% identical), pig MRPL20 (87% identical), rat Mrpl20 (87% identical), tropical clawed frog mrpl20 (73% identical), chimpanzee MRPL20 (68% identical), zebrafish mrpl20 (62% identical), Drosophila melanogaster mRpL20 (36% identical), Caenorhabditis elegans mrpl-20 (23% identical).
Diseases named in the same sentence as MRPL20 in open-access papers:
MRPL20 is named in the same sentence as 6 diseases in open-access papers, as found by Europe PMC text mining. Sharing a sentence is not in itself a finding about the gene and the disease. The quoted sentences say what the papers report.
asthma (1 paper, 2026). "Differentially methylated loci were near genes related to asthma (ITPR2, MAPK1), lung function (FKBP11), mitochondrial function (MRPL20, SPTBN1), inflammation (C3), and immune function (N4BP3, EIF5)." (PMID 41749276, 2026).
colorectal cancer (1 paper, 2024). A primary or metastatic malignant neoplasm that affects the colon or rectum. "Conversely, MRPL20, was found to limit metastasis in colorectal cancer." (PMID 39354291, 2024). "Differential expression of MRPL20 has been observed in prostate and colorectal cancers." (PMID 39354291, 2024).
tumor (1 paper, 2024). "MRPL20 contributes to tumor cell migration and invasion by affecting the energy metabolism and proliferation ability of tumor cells through regulating the function of mitochondria." (PMID 39529627, 2024). "Further studies revealed that the hub genes MRPL20, COL4A1, and VWF played key roles in tumor energy metabolism, cell adhesion, and angiogenesis, showing the possibility of inhibiting BC cell development and metastasis by regulating these genes and their interactions." (PMID 39529627, 2024).
MRPL20 also shares sentences with these, for which no sentence is quoted: breast carcinoma (1 paper); myocardial ischemia (1); prostate carcinoma (1).